INS (insulin)
Diseases named in the same sentence as INS in open-access papers (continued):
Sharing a sentence is not in itself a finding about the gene and the disease.
diabetes (continued). "As part of diabetes self-management, they are being taught to monitor their carbohydrate intake through carbohydrate counting, or “carb counting,” which is a meal planning technique for managing blood glucose levels in balance with medication or insulin intake and physical activity." (PMID 30995902, 2019). "Regarding glycemic control among patients with diabetes, prescription of oral antidiabetics such as metformin, with or without associated prescription of insulin, may be necessary to improve the effectiveness of treatment." (PMID 31691770, 2019). "Therefore, implementing a guided self-determination approach (e.g., based on empowerment) that supports problem-solving and decision-making related to insulin therapy in adolescents with T1DM may improve their motivation to manage their diabetes care." (PMID 31183368, 2019). "Whether early recruitment of anti-insulin B cells to the pancreas after global B cell depletion contributes to disease persistence or, alternatively, may in some way participate in the delay of diabetes needs to be addressed." (PMID 31444529, 2019). "Two pages, 1 with a disclaimer, made explicit claims that diabetes medications recommended by health professionals are extremely dangerous and should be avoided (eg, “Avoid these 3 doctor recommended treatments: oral medication, insulin therapy, [and] other injectables”)." (PMID 30735144, 2019). "Diabetes mellitus (DM) is a prevalent metabolic disorder which is characterized by chronic hyperglycemia resulting from defective insulin production, insulin response, or both (Jain and Jangir, 2014 ▶)." (PMID 31309073, 2019). "One study pointed out that patients with diabetes who are smokers had a higher average hemoglobin A1c and higher insulin resistance than those who are nonsmokers, which supports our findings that older patients with diabetes who are smokers have an increased risk of diabetes-related ED visits." (PMID 31858955, 2019). "However, for diabetes, these amino acids have adverse effects on insulin sensitivity (46, –, 48)." (PMID 31164448, 2019). "In recent years, the administration of intranasal insulin and of drugs which enhance cell sensitivity to this hormone was shown to improve cognitive function in patients with Alzheimer’s disease, mild cognitive impairments, or diabetes mellitus, as well as in animal models of these diseases." (PMID 31362343, 2019). "However, several factors are related to adherence to treatment for hypertension and diabetes in Primary Health Care, including the proximity of the primary care source to the users of the health service, a conditional factor for people with diabetes who use insulin." (PMID 31783845, 2019). "Because it was shown that oxidants can amplify GSIS and persistent activation of Nrf2 decreases glucose-triggered ROS signaling insulin release, this study points out on distinct roles that Nrf2 may play in pancreatic β-cell dysfunction that accompanies different stages of diabetes." (PMID 30450940, 2019). "Diabetes may be related to AD through mediating oxidative stress and protein glycosylation; however, peripheral insulin could directly damage normal brain structures and functionality by crossing the BBB to act on insulin receptors located in the central nervous system (CNS)." (PMID 31649504, 2019). "Thus, senolytics may alleviate senescence‐associated complications of metabolic dysfunction, beyond the impact of glucose‐lowering and insulin sensitization that senolytics share with certain currently available diabetes treatments." (PMID 30907060, 2019). "Therefore, timely and effective glycemic control with diet, sulfonylurea, metformin, or insulin, improvements in glycolipid metabolism, and increases in insulin sensitivity play an irreplaceable role in the treatment of diabetes and the prevention and treatment of complications." (PMID 30823412, 2019). "Indeed, MUFAs display beneficial effects on insulin sensitivity and type 2 diabetes mellitus." (PMID 31554181, 2019).
diabetes (continued). "This gold nanocluster-based responsive insulin-releasing system mimics the function of blood glucose regulation of the pancreas in the body, which may have great applications in the theranostics in diabetes." (PMID 31159842, 2019). "Since the publication of a study by the University Group Diabetes Program in 1970, concerns have been raised about the long-term CV safety of SUs after an increased occurrence of CV mortality was observed among SU-treated patients versus patients managed with diet alone or diet plus insulin." (PMID 30876392, 2019). "Diabetes mellitus (DM)is a disease which develops as a result of dysfunction in the activation or expression of insulin and in which impairments are seen in cellular and humoral immunity in the long term." (PMID 31673265, 2019). "Finally, psychological stress, through β-cell stress or direct influence on the immune system, may decrease insulin sensitivity and increase insulin resistance, so contributing to the induction or progression of diabetes-related autoimmunity." (PMID 31555211, 2019). "Likewise, diabetes mellitus is a major cause of mortality and the most common metabolic disorder characterized by hyperglycemia due to lack of insulin production by the pancreas or the inability of the insulin produced to control blood glucose." (PMID 31061671, 2019). "Therefore, diabetes-related effects on testicular function may be a consequence of reduced insulin signaling and defective energy metabolism, although direct effects of hyperglycaemia cannot be excluded." (PMID 31620084, 2019). "For instance, Rb1 has a significant antihyperglycemic effect and increases insulin sensitivity, and is thus used clinically to treat diabetes mellitus (DM)." (PMID 31277214, 2019). "Diabetes mellitus (DM) is a chronic disease characterised by the body’s inability to produce insulin or use it efficiently." (PMID 31109110, 2019). "Obesity and reduced insulin sensitivity may be key features for diabetes in Tally-Ho mice." (PMID 31466386, 2019). "Further studies are necessary to investigate the impact of Sfrp5 on insulin secretion in isolated islets and/or primary beta cells from rats and humans and to evaluate whether Sfrp5 might be of therapeutic interest for the treatment of obesity and diabetes." (PMID 30921355, 2019). "We will firstly describe the role of ion channels and transporters in relation to insulin secretion from the pancreatic beta-cell and then describe mechanistic insights into how defects in ion channels and transporters lead to hyperinsulinaemic hypoglycemia and diabetes mellitus." (PMID 31137773, 2019). "Insulinomas show elevated serum insulin levels; however, other conditions might lead to increased serum insulin, most notably impaired glucose tolerance, diabetes mellitus type 2, administration of exogenous insulin (factitious hypoglycemia) and sulfonylurea-induced hypoglycemia." (PMID 31382663, 2019). "Diabetes mellitus (DM) is a progressive metabolic disease characterized by an imbalance in glucose homeostasis, impaired insulin secretion, and abnormal lipid and carbohydrate metabolism." (PMID 31134090, 2019). "Also, the role of galangin in combination with insulin was evaluated for the proliferative effect and glucose metabolism, in the case of the skeletal muscle system, to reveal the potential of combination therapy to treat diabetes mellitus." (PMID 30862104, 2019). "In addition to the dichotomous outcomes, we investigated whether baseline plasma protein levels were prospectively associated with the diabetes-related continuous outcomes fasting glucose, OGTT 2-h-glucose, fasting insulin, and insulin resistance." (PMID 30599058, 2019). "As such, we aimed to comprehensively characterise the prescribing practices of specialist diabetes healthcare professionals across Central and South-Eastern European countries and assess the factors that influence their clinical decision-making regarding insulin initiation in T2D." (PMID 30993528, 2019).
diabetes (continued). "Hypoglycemia is a common complication of insulin therapy in patients with Type 1 Diabetes Mellitus (DM)." (PMID 31651281, 2019). "An abnormal increase in blood glucose may be due to a defect in insulin self-secretion caused by the immune system (type 1 diabetes mellitus, T1DM), or resistance to the cellular effects of insulin, as well as insufficient insulin secretion (type 2 diabetes mellitus, T2DM)." (PMID 31511772, 2019). "Diabetes Mellitus (DM) is a progressive disease which often requires insulin therapy during the course of the disease." (PMID 31086522, 2019). "Diabetes mellitus (DM) or simply diabetes is a serious, chronic disease that occurs either because of inadequate insulin production by the pancreas or inability to effectively utilize insulin by the body." (PMID 31454396, 2019). "PSG-1 significantly reduced serum total cholesterol, triglyceride, LDL levels, and increased insulin sensitivity and HDL levels, which is important because dyslipidemia is a strong risk factor for the development of cardiovascular disease in patients with diabetes." (PMID 31717970, 2019). "Diabetes mellitus (DM) is a chronic metabolic syndrome characterized by prolonged hyperglycemia caused by either insulin secretion disorders, a lack of sensitivity of the cells to insulin, or both." (PMID 31583254, 2019). "Diabetes mellitus (DM) is a disease characterized by persistent hyperglycemia, either due to an autoimmune destruction of pancreatic β-cells and impaired production of insulin (Type 1 DM), or due to the failure of peripheral tissues to respond properly to insulin (Type 2 DM)." (PMID 31777357, 2019). "Therefore, sitagliptin represents the introduction of an expensive brand name drug, considered a moderately novel diabetes treatment, into a market that contained a large number of both generic and brand name treatment options, plus multiple, highly expensive, insulin alternatives." (PMID 31619229, 2019). "Therefore, hyperinsulinemia resulting from either insulin resistance or prolonged insulin administration for the treatment of diabetes may potentially lead to the development of lung cancer." (PMID 31354621, 2019). "Diabetes mellitus (DM) is a group of metabolic disorders characterized by hyperglycemia due to defects in insulin secretion, insulin action, or both." (PMID 30651718, 2019). "SP induces a marked increase in insulin secretion from the pancreas of healthy rats, but inhibits insulin secretion from the pancreas of diabetic rats, indicating that it may play a role in the onset of diabetes." (PMID 30842720, 2019). "Liu and co-workers (2017) provided new evidence that demonstrates the ability of cAMP signaling to enhance [Ca+2]int, and insulin secretion is also due to the inhibition of Kv channels; it is suggested that the cAMP/Kv channel pathway could be a therapeutic strategy for diabetes treatment." (PMID 31091684, 2019). "People in the current study altered their diabetes management regimes if undesirable outcomes were experienced, new information regarding their current therapy was received and if they were unable to secure medications or necessary equipment such as insulin or BGL monitors." (PMID 30794570, 2019). "Type 1 Diabetes Mellitus (DM) is usually diagnosed in children and adolescents and is characterized by pancreatic beta-cell dysfunction and impaired insulin secretion." (PMID 31651281, 2019). "Diabetes mellitus (DM) is a metabolic disease characterized by chronic hyperglycemia resulting from impaired insulin secretion and/or action." (PMID 31887984, 2019). "Diabetes mellitus (DM), an epidemic metabolic disorder, is characterized by hyperglycaemia and hyperinsulinaemia resulting from not only impaired insulin secretion, but also insulin resistance." (PMID 30804434, 2019).
diabetes (continued). "One study reported a high prevalence of serum hypertonicity among dogs with diabetic ketosis before insulin treatment was begun and another found that hyperosmolarity and hypertonicity were common pre-treatment findings in a group of 66 dogs with complicated diabetes." (PMID 31335875, 2019). "FOXO proteins are crucial in diabetes as they are highly expressed in the major insulin target tissues and play multiple and complex roles as both overexpression of constitutively active FOXO1α and knockdown of FOXO1/3α could lead to diabetes or hypertriglyceridemia." (PMID 31949875, 2019). "Similarly, for the diabetes outcomes, high adherence to the TMexD was associated with lower insulin concentrations and with a lower risk or having pre-diabetes in observational studies, but not with glucose levels (in either the cohort study or the RCT)." (PMID 31744179, 2019). "There is a need for greater support from the diabetes team during pregnancy for technical assistance and intensified focus on postprandial hyperglycaemia, including dietary advice/carbohydrate counting and a supported active approach to prandial insulin adjustments." (PMID 30904938, 2019). "Thus, the sympathoadrenal, and presumably the cardiovascular response to hypoglycemia may rely upon a complex interaction of multiple factors, including duration of diabetes, insulin exposure and BB use and type, and requires further study." (PMID 31775749, 2019). "Finally, we present evidence to suggest that targeting SHP2 might be a viable strategy to increase insulin sensitivity and treat diabetes." (PMID 30931927, 2019). "Nigella sativa was shown to significantly improve laboratory parameters of hyperglycemia and diabetes control after treatment with a significant fall in fasting blood glucose, blood glucose level 2 h postprandial, glycated hemoglobin, and insulin resistance, and a rise in serum insulin." (PMID 31817324, 2019). "Over the past decade, more than 50 new insulin gene mutations have been reported to cause proinsulin misfolding and mutant INS-gene–induced diabetes of youth (MIDY), highlighting important pathogenesis of proinsulin misfolding in the development and progression of diabetes." (PMID 31311313, 2019). "In diabetes, oxidative stress is mainly caused by an excessive increase of glucose, Free Fatty Acids (FFA), and/or inflammatory mediators which, in turn, cause mitochondrial dysfunction and/or Endoplasmic Reticulum (ER) stress with consequent insulin resistance and β cell dysfunction." (PMID 31861156, 2019). "A recent study suggested that PPARγ activation may decrease the progression of atherosclerosis and increase insulin sensitivity, and may be a potential therapeutic target for the treatment of various diseases, including type 2 diabetes mellitus and dyslipidemia." (PMID 30818882, 2019). "Therefore, in this study, we employed a rat model of STZ-induced diabetes to test whether swimming training improves the strength of the femoral neck in young rats under insulin therapy." (PMID 31038563, 2019). "However, insulin-treated diabetes was not identified as an independent risk factor for higher mortality in the first (HR 1.29; 95% CI 0.97–1.72, p = 0.084) and 3rd years (HR 1.21; 95% CI 0.98–1.49; p = 0.079) after multivariable adjustment." (PMID 31138207, 2019). "Altered insulin signaling in diabetes may play a detrimental role in GnRH signaling." (PMID 31620084, 2019). "Diabetes is associated with a series of changes in endothelial function caused by several factors including an excess of plasma FFAs in T2DM and alterations in glucose metabolism, impaired insulin signalling, chronic inflammation and oxidative stress in both T1DM and T2DM." (PMID 31888259, 2019). "Diabetes mellitus (DM) is a group of metabolic diseases characterized by hyperglycemia resulting from defects in insulin secretion, response to insulin, or both." (PMID 31467816, 2019).
diabetes (continued). "Hypertriglyceridemia is common in patients with diabetes (>30-60%), and it is known to be transiently elevated by uncontrolled hyperglycemia usually in the setting of recent diabetes diagnosis or poor glycemic control (due to inadequate insulin activity and lipolysis)." (PMID 30891069, 2019). "Diabetes mellitus (DM) is a chronic metabolic disorder from genetic and/or environmental etiology characterized by increased levels of blood glucose due the impairment in insulin production or its secretion/action." (PMID 31261912, 2019). "Although pharmacological therapies for prevention of T2D have not yet been recommended by the American Diabetes Association and have not been approved by the U.S. Food and Drug Administration, insulin-sensitizing agents have been found to reduce T2D risk by 31–77%." (PMID 30934836, 2019). "We think that patients with RM or RIF of unknown etiology diagnosed with thyroid autoimmune disorders, family history of diabetes and impaired insulin response after OGTT could be considered as a subset of patients, candidates for further specific autoimmune tests to rule out DAA." (PMID 30346951, 2018). "In addition, they also inhibit insulin degradation and improve glucose utilization and may be relevant in the management of diabetes." (PMID 30510713, 2018). "The pancreas is an important organ in diabetes, because it secrets two glucose-regulating hormones—insulin and glucagon—and honey might protect this organ against oxidative stress and damage with its antioxidant molecules, this being another potential mechanism of hypoglycemic effect of honey." (PMID 29507651, 2018). "Therefore, it was reasonable to believe that elderly diabetes with more than 10 years’ duration had a higher tendency to be treated with insulin because of the progression of disease itself, which consequently might result in higher positivity of IAA." (PMID 29887833, 2018). "We previously identified basal-bolus insulin therapy as underutilized in postoperative patients with diabetes mellitus (DM), despite evidence of ongoing hyperglycemia." (PMID 29255628, 2018). "Moreover, insulin treatment by itself was shown to be associated with significantly worse cardiovascular outcomes after PCI compared to non-insulin treated diabetes." (PMID 29402330, 2018). "Medication records may be used to supplement clinical data in identifying individuals with diabetes but this can present additional problems (e.g. metformin is used for the treatment of polycystic ovary syndrome and insulin is used in both type 1 and type 2 diabetes)." (PMID 29247363, 2018). "Diabetes mellitus (DM) is a chronic metabolic disorder characterized by hyperglycemia resulting from the malfunction in insulin secretion and/or insulin action, both leading to impair metabolism of carbohydrates, lipids, and proteins." (PMID 30186162, 2018). "Moreover, second generation antipsychotics (SGAs) have a marked propensity to induce increased levels of blood glucose, glycosylated hemoglobin and insulin, higher IR, alterations of blood lipid profiles, weight gain and sometimes frank diabetes mellitus (T2DM)." (PMID 30068291, 2018). "Although the late insulin secretion may keep the subjects with a nonpositive insulin response from the development of diabetes, they are likely to have a higher risk of diabetes compared with the IFG and/or IGT with insulinogenic index ≥ 0.4." (PMID 29765987, 2018). "However, tumor size (an important factor for detection) was not related to diabetes status or insulin exposure, so it is unlikely that the associations we observed were due to reverse causation." (PMID 29486734, 2018). "On the other hand, for patients with diabetes who are undergoing surgery, appropriate glycemic control throughout the perioperative period needs to be maintained to conserve the endocrine-metabolic balance between insulin and hyperglycemia-promoting hormones, such as cortisol and adrenaline." (PMID 30526578, 2018).